ATP13A2 (ATPase cation transporting 13A2)
Diseases named in the same sentence as ATP13A2 in open-access papers (continued):
Sharing a sentence is not in itself a finding about the gene and the disease.
multiple sclerosis (2 papers, 2024 to 2025). A progressive autoimmune disorder affecting the central nervous system resulting in demyelination. "This study identified IREB2, LAMP2, ISCU, ATP6V1G1, ATP13A2, and SKP1 as genes associated with multiple sclerosis (MS) and iron metabolism, establishing their multi-gene diagnostic value for MS with an AUC of 0.83." (PMID 38590521, 2024).
adenoma (1 paper, 2024). A neoplasm arising from the epithelium. "Noteworthy, the numbers of RNA interactors of some MP-RNAs (WDR62, TGFBR3, RN7SL5P, RMRP, MIR663AHG, AJ009632.2, CDKL1, OPRD1, PLOD1, AL117692.1, ATP13A2, EPB41) in cancer tissue were significantly increased compared with that in paracancer and adenoma." (PMID 38773399, 2024).
cervicitis (1 paper, 2025). An acute or chronic inflammatory process that affects the cervix. "ATP13A2 expression levels in epithelial tissues of cervicitis samples were markedly lower than those in cervical squamous epithelial cancer tissues, indicating a potential differential diagnostic value." (PMID 40197818, 2025). "In contrast, cervicitis samples exhibited lower ATP13A2 staining in epithelial and stromal tissues." (PMID 40197818, 2025).
familial Mediterranean fever (1 paper, 2013). Familial Mediterranean fever (FMF) is an autoinflammatory disorder characterized by recurrent short episodes of fever and serositis resulting in pain in the abdomen, chest, joints and muscles. "The same principle applies to other genes: ATP13A2 responsible for a juvenile onset of PD, GBA responsible for Gaucher’s disease, ABCA1 responsible for Tangier disease, and MEFV responsible for familial Mediterranean fever (FMF)." (PMID 23970884, 2013).
neuropathy (1 paper, 2019). A disorder affecting the nervous system that manifests with pain, tingling, numbness, and/or muscle weakness. "We prioritized the functional testing of the ATP13A2 variant predominantly due to its known association with neurodegenerative disorders and neuropathy." (PMID 30992063, 2019).
pantothenate kinase-associated neurodegeneration (1 paper, 2013). "In addition to the core syndromes of pantothenate kinase-associated neurodegeneration (PKAN, NBIA1) and PLA2G6-associated neurodegeneration (PLAN, NBIA2), several other genetic causes have been identified (including FA2H, C19orf12, ATP13A2, CP and FTL)." (PMID 23814539, 2013).
progressive myoclonus epilepsy (1 paper, 2012). A rare group of disorders characterized by the development of myoclonic and tonic-clonic epileptic seizures associated with progressive degeneration of the nervous system. "Most of these known canine progressive myoclonus epilepsy (PME) genes are orthologues of the corresponding human syndromes and two new NCL candidate genes, ARSG and ATP13A2, have been identified for human NCLs." (PMID 22457775, 2012).
Spastic paraplegia (1 paper, 2020). Complete loss of the ability to move the lower limbs accompanied by spasticity of the lower limbs. "We describe three unrelated patients with predominant spastic paraplegia features, harboring homozygous ATP13A2 mutations that are either novel or were not previously reported in HSP." (PMID 31944623, 2020).
Zinc deficiency (1 paper, 2012). A deficiency of the essential metal Zinc; an essential cofactor for many enzymes. "It is possible that reduced expression of ATP13A2, which has been shown to reduce cellular manganese concentrations, occurs in response to severe zinc deficiency in our model, and a recent study revealed that ZnT10 (Slc30a10) plays a key role in manganese transport in humans." (PMID 22737083, 2012).
neurodegenerative disease (13 papers, 2012 to 2025). A disorder of the central nervous system characterized by gradual and progressive loss of neural tissue and neurologic function. "Indeed ATP13A2, being a lysosomal polyamine exporter, has a protective role in lysosomes; and its loss of function has been implicated in a wide variety of neurodegenerative diseases." (PMID 39981745, 2025). "Our study demonstrates that the adult-onset homozygous deletion of ATP13A2 in the nigrostriatal pathway produces robust and progressive dopaminergic neurodegeneration that serves as a useful in vivo model of ATP13A2-related neurodegenerative diseases." (PMID 39030200, 2024). "As ATP13A2 has a role in intracellular transport and vesicle trafficking, dysfunction of these processes in other neurodegenerative diseases may also impact on ATP13A2." (PMID 24252509, 2013). "In addition, our findings on the activity regulation of ATP13A2 through lipids binding to NTD may offer a modality to therapeutically activate the ATP13A2 function to protect against neurodegenerative diseases." (PMID 34728622, 2021). "A growing body of evidence indicates that the cation-transporting ATPase 13A2 (ATP13A2) and PAs play a key role in the endo-lysosomal system and mitochondrial function, which are at the heart of neurodegenerative diseases." (PMID 35885061, 2022). "The identification of CLN12 (ATP13A2) in a rare case of Juvenile NCL reminds of the relevance of other yeast models in NCLs and neurodegenerative disease." (PMID 31655107, 2020).
cancer (12 papers, 2020 to 2026). A tumor composed of atypical neoplastic, often pleomorphic cells that invade other tissues. "Together, these findings underscore the broader physiological and pathological significance of intracellular P-type K+-ATPases and highlight α3NaK and ATP13A2 as promising therapeutic targets in cancer metastasis and PD." (PMID 41751935, 2026). "Among them, the P2-type Na+,K+-ATPase and the P5-type ATP13A2 have recently emerged as key regulators of cancer progression and neurodegeneration, respectively." (PMID 41751935, 2026). "In particular, correlations have been described between ATP13A2 and cancer progression, metastasis and immune infiltration in HCC cells." (PMID 40197818, 2025). "This investigation revealed that ATP13A2 expression was significantly upregulated in cancer tissue samples." (PMID 40197818, 2025). "In the literature related to ATP13A2 and cancer, only one study preliminarily confirmed that downregulation of ATP13A2 can suppress tumourigenesis by blocking autophagic flux in CRC." (PMID 37243374, 2023). "A significant increase in ATP13A2 expression was found in cancer tissues from patients with CRC compared with adjacent normal tissues." (PMID 37243374, 2023). "However, many studies have also reported abnormal expression patterns of ATP13A2 in various cancers, notably colorectal and hepatic cancers." (PMID 40197818, 2025). "In contrast, we observed contradictory effects of LPS including the increased proliferation and expression of several tumor-associated genes and the decreased expression of other cancer-associated genes in tumor enteroids including LOC610994 (Zeta Crystallin), Gpatch4, SLC7A1, ATP13A2, and TEX45." (PMID 35884586, 2022). "Therefore, silencing of ATP13A2 in vivo significantly reduced tumor sizes, suggesting that ATP13A2 is a potential target for cancer therapy." (PMID 33308286, 2020). "Interestingly, while LPS treatment increased the proliferation and expression of the GEN1, KRIT1, CENPF, CPLANE1, STYK1, and KHDRBS3 genes, it decreased the expression of the cancer associated LOC610994, Gpatch4, SLC7A1, ATP13A2, and TEX45 genes in tumor enteroids." (PMID 35884586, 2022). "While LPS incubation resulted in a pro-cancer gene expression pattern and stimulated proliferation of IBD enteroids and colonoids, downregulation of several cancer-associated genes such as Gpatch4, SLC7A1, ATP13A2, and TEX45 was also observed in tumor enteroids." (PMID 35884586, 2022).
tumor (9 papers, 2015 to 2025). "Immunohistochemical analysis revealed that ATP13A2 was positively expressed in 80% (24 cases) of tumour tissues, with strong positivity in 50% (15 cases)." (PMID 40197818, 2025). "As a verification of the results of the analysis of these publicly available databases, we assessed the expression levels of ATP13A2 in 30 pairs of CRC tumour tissues and adjacent normal tissues." (PMID 37243374, 2023). "IHC staining of mouse tumours revealed that ATP13A2−/− mice displayed significantly lower Ki67 and PGD protein expression than ATP13A2+/+ mice." (PMID 37243374, 2023). "Then, we knocked down ATP13A2 with a lentivirus through intratumoural injection and found that the tumour volume and weight in the sh‐ATP13A2 group were lower than those in the control group." (PMID 37243374, 2023). "Ki67 expression was decreased in tumours derived from ATP13A2‐KO cells and increased in tumours derived from ATP13A2‐OE cells." (PMID 37243374, 2023). "In our next step, we summarized the clinicopathological characteristics of the 30 patients in the first cohort, and tumour sizes were larger in patients with high ATP13A2 expression than in those with low ATP13A2 expression." (PMID 37243374, 2023). "Since autophagy and PPP crosstalk occur in tumours, ATP13A2 likely exerts a similar effect on the PPP." (PMID 37243374, 2023). "ATP13A2−/− mice also had a significantly lower number of tumours and smaller tumour size than ATP13A2+/+ mice." (PMID 37243374, 2023). "Western blotting also showed that the expression of ATP13A2 was significantly higher in tumor tissues than that in the paired normal tissues." (PMID 33308286, 2020). "Patients with M0 stage tumors showed only CACNA1H, SLC24A3 and NALCN associated with OS differences, while ATP2A1, ATP13A2, TRPC1, and NALCN proved to be significantly associated with OS in the N1–N3 tumor stage patient subgroup." (PMID 31083561, 2019). "Given the association between SLC39A14 and ATP13A2 and the similarities in immune and prognostic profiles, we hypothesize that ATP13A2 may promote tumour progression through an ion channel mechanism similar to SLC39A14, which may cooperate with other genes." (PMID 40197818, 2025). "Additionally, tumour bacterial infiltration was assessed using weighted co‐expression network analysis, revealing a relationship between ATP13A2 expression and bacteria in the CC tumour microenvironment." (PMID 40197818, 2025). "According to a previous gene enrichment analysis, the role of microbiota and ATP13A2 in promoting tumour progression may be regulated by transcription." (PMID 40197818, 2025). "Clinical analysis showed that most tumours were positive for both ATP13A2 and P16." (PMID 40197818, 2025). "Finally, we constructed an AOM/DSS model to further evaluate the effect of tumour therapy targeting the ATP13A2 gene." (PMID 37243374, 2023). "Activation of the PPP plays an important role in tumour proliferation, and ATP13A2 may have the same role as a PPP‐related gene." (PMID 37243374, 2023). "Notably, tumours derived from ATP13A2‐KO cells were smaller and lighter, whereas tumours derived from ATP13A2‐OE cells were larger and heavier than those in the control group." (PMID 37243374, 2023). "As expected, the mRNA level of PGD in tumour of ATP13A2−/− mice decreased." (PMID 37243374, 2023). "After LPS treatment, another important gene, ATP13A2, was downregulated in tumor enteroids." (PMID 35884586, 2022). "Moreover, ATP13A2 is associated with CD8+ T cells and promotes tumour growth in HCC." (PMID 40197818, 2025). "Given these similarities, we speculated a crucial role of ATP13A2 in tumour progression." (PMID 40197818, 2025). "Prognostic genes including EZH2, PCNA, and BIRC5 were specifically expressed in epithelial clusters, while CHMP4C, ATP13A2, and ALDOA showed broader expression patterns, supporting their tumor-specific roles." (PMID 40678068, 2025).
tumor (continued). "Here, we show for the first time the important role of PGD in CRC development elucidate the specific mechanism of the ATP13A2‐TFEB‐PGD signaling axis, complement the relationship between PGD and tumours, and partially explain the effect of ATP13A2 on CRC." (PMID 37243374, 2023). "ATP13A2 and MCOLN2 protein expression levels were reduced in tumor samples when compared with normal ones, in line with the association of a better prognosis with a lower mRNA expression." (PMID 31083561, 2019). "ATP13A2 has a mutation frequency of only 4% in CRC, indicating that its mutation does not explain its role in tumours." (PMID 37243374, 2023). "Collectively, our results suggest that ATP13A2 affects PGD expression to regulate the PPP, which not only promotes the proliferation of CRC cells but also enhances their ability to resist oxidative stress, supporting CRC cell survival in the real tumour environment." (PMID 37243374, 2023). "One hundred and fourteen matched human NSCLC tumor/normal pairs were examined by real-time q-PCR analysis for expression of PARK1/4 (SCNA), PARK2 (Parkin), PARK5 (UCHL1), PARK6 (PINK1), PARK7 (DJ-1), PARK8 (LRRK2), PARK9 (ATP13A2), PARK15 (FBXO7), and GBA mRNA." (PMID 26245297, 2015).
neurological disorders (3 papers, 2014 to 2024). "To date, it is evident that numerous neurological disorders have been linked to ATP13A2 with diverse and complex neurological deficits, complicating our understanding of ATP13A2." (PMID 39090150, 2024). "A major bottleneck in unraveling the role of ATP13A2 in neurological disorders is the fact that virtually nothing is known concerning the molecular function and substrate specificity of the P5B-type ATPases." (PMID 24904274, 2014). "Also, the dysfunction of ATP13A2 and ATP13A4 are linked to various neurological disorders." (PMID 29505581, 2018).
movement disorder (1 paper, 2021). Neurological conditions resulting in abnormal voluntary or involuntary movement, which may impact the speed, fluency, quality and ease of movement. "This Movement Disorder Society Genetic mutation database Systematic Review focuses on monogenic atypical parkinsonism with mutations in the ATP13A2, DCTN1, DNAJC6, FBXO7, SYNJ1, and VPS13C genes." (PMID 34396589, 2021).
ATP13A2 also shares sentences with these, for which no sentence is quoted: hereditary spastic paraplegia (8 papers); cognitive decline (4); Parkinson disease 9 (4); melanoma (3); aceruloplasminemia (2); acute myeloid leukemia (2); Alzheimer disease (2); Bradykinesia (2); cervical cancer (2); genetic disease (2); hepatocellular carcinoma (2); hereditary ataxia (2); Intellectual disability (2); non-small cell lung carcinoma (2); Age-related cataract (1); Aphasia (1); autism (1); autism spectrum disorder (1); autosomal recessive spastic paraplegia type 78 (1); cardiovascular diseases (1); cataract (1); Cerebral atrophy (1); corticobasal degeneration (1); corticobasal syndrome (1); Creutzfeldt-Jakob disease (1); deafness (1); dopaminergic neuroblastoma (1); Dyskinesia (1); Gaucher disease (1); Gaucher disease type 3 (1).
A further 27 diseases each share a sentence with ATP13A2 in 1 paper.